VCP (valosin containing protein)
Diseases named in the same sentence as VCP in open-access papers (continued):
Sharing a sentence is not in itself a finding about the gene and the disease.
Paget disease (32 papers, 2008 to 2025). A malignant neoplasm composed of large cells with large nuclei, prominent nucleoli, and abundant pale cytoplasm (Paget cells). "Mutations in VCP were already known to underlie an unusual clinical syndrome characterized by inclusion body myopathy, Paget's disease of the bone and FTD (IBMPFD), or multisystem proteinopathy." (PMID 35273561, 2022). "We reported the first VCP mutation carrier manifesting ALS with Paget's disease of bone in the Chinese population." (PMID 35197922, 2022). "Mutations in valosin-containing protein (VCP) cause inclusion body myopathy and Paget disease of the bone and have been shown to alter autophagosome maturation and autophagy impairment." (PMID 27484057, 2016). "For example, mutations in the ER-associated ATPase p97/VCP have been associated with a specific type of inclusion body myopathy associated with Paget disease." (PMID 18270596, 2008). "The association of inclusion body myopathy and Paget’s disease are indicative of VCP mutations." (PMID 26388768, 2015). "To elucidate the role of VCP in neurodegenerative processes in ALS, in the present study we examined the neuropathology of a patient with ALS and Paget disease of bone with a novel VCP mutation, as well as the immunohistochemical localization of VCP in SALS cases and in the ALS-VCP patient." (PMID 25492614, 2014). "Mutations in VCP have been suggested to be involved in the pathogenesis of ALS, frontotemporal dementia, and Paget’s disease." (PMID 36836867, 2023). "The newly obtained rodent models expressing mutant VCP exhibit the symptoms of Paget’s disease accompanied by progressive muscular weakness and significant accumulation of cytoplasmic TDP-43 in neurons of the brain and in spinal cord motor neurons." (PMID 36836867, 2023). "Type D pathology is directly associated with patients with inclusion body myopathy with early onset Paget’s disease and FTD (IBMPFTD) caused by valosin-containing protein (VCP) mutations." (PMID 30875755, 2019). "In 2004, the gene encoding valosin-containing protein (VCP) gene was found, located on chromosome 9p13.3, which is associated with the genes that cause FTLD in association with inclusion body myopathy and Paget’s disease." (PMID 23597030, 2013). "In this study, we did not observe the classic phenotypes of mutations in VCP, such as inclusion body myopathy with Paget’s disease of the bone, we will follow up the patient to see the symptoms evolve." (PMID 34389718, 2021). "Similarly, genes such as TANK-binding kinase-1 (TBK1), Sequestosome-1 or p62 (SQTSM1), Optineurine protein (OPTN), and Valosin-containing protein (VCP) that are associated with FTD, inclusion body myositis, motor neuron disease, and Paget's disease encode proteins related to protein degradation." (PMID 35115992, 2021).
dementia (26 papers, 2008 to 2025). Loss of intellectual abilities interfering with an individual's social and occupational functions. "Reports on small number of cases have linked specific VCP mutations exclusively to Charcot–Marie‐Tooth43 or dementia." (PMID 36861178, 2023). "Mutations in the VCP gene produce in most of the patients a myopathy that can be associated with other phenotypes such as dementia, PDB, motor neuron disease or polyneuropathy." (PMID 37603075, 2023). "Since VCP mutations are associated with so many phenotypes, it is included in panels to investigate genetic causes of myopathy, dementia, and ALS." (PMID 35741724, 2022). "The function of VCP in spinogenesis provides a potential explanation how VCP mutations result in dementia in patients." (PMID 22449146, 2012). "It has been suggested that the same biochemical process occur in humans, in which VCP/p97 gain-of-function mutations lead to a syndrome leading to myopathy, bone anomalies and, often, dementia." (PMID 20979629, 2010). "While usual clinical phenotype of VCP mutation carriers is characterized by neuropsychiatric manifestations compatible with bvFTD, cases of semantic variant primary progressive aphasia (svPPA) and dementia of the Alzheimer type have also been reported." (PMID 34917136, 2021). "Although the molecular mechanism underlying IBMPFD pathogenesis is still unclear, the accumulated evidence indicates that VCP plays critical roles in neuronal morphogenesis, which may account for the dementia phenotype associated with IBMPFD patients." (PMID 22449146, 2012). "Furthermore, different mutations in MATR3-related disease may cause either ALS or distal myopathy, and dementia/lower motor neuron syndrome can coexist with myopathies due to VCP mutations (OMIM #167320)." (PMID 26999347, 2016). "Tau phosphorylation was also increased in VCP mutant neurons compared with controls, including at Ser404 and Ser202/Thr205 (AT8), epitopes frequently associated with tau-mediated dementias." (PMID 37882537, 2024). "AKT1 can induce tumour formation through the upregulation of RNA binding protein EIF4G137, coronavirus exit from endosomes via valosin-containing protein VCP38 and MAPT-associated tau protein formation in dementia-like cognitive impairment." (PMID 36229517, 2022). "On the other end of the process, dementia can be caused by mutations of presenilin-1, endosomal sorting complexes required for transport (ESCRT) machinery or valosin-containing protein (VCP)/p97." (PMID 28837083, 2017). "Valosin containing protein (VCP) mutations have been linked with ALS and other degenerative diseases, including dementia." (PMID 26973461, 2016). "No other pathogenic mutation in genes known to be associated with neurodegenerative diseases, and/or rare genetic causes of dementia, such as mutations in CHMP2B, FUS, TARDBP, SQSTM1 and VCP have been identified." (PMID 27632209, 2016). "Patient carrying the Y1587delta mutation presents clinically with short stature and dementia, which echo the functions of VCP in dementia and bone metabolism." (PMID 22449146, 2012). "Both NF1 and VCP/p97 are critical for dendritic spine formation, which provides the cellular mechanism explaining the cognitive deficits and dementia found in patients." (PMID 22449146, 2012). "Valosin-containing protein was previously reported to have antioxidant properties which could help in neuronal syndromes such as Alzheimer’s disease, lateral sclerosis and dementia." (PMID 34361776, 2021). "Mutations in p97/VCP cause inclusion body myopathy with early-onset Paget’s disease, and a late-onset frontotemporal dementia (IBMPFD) disease characterized by muscle weakness, bone deformities and weakness, and dementia." (PMID 33467597, 2021). "Hence we sought to evaluate the semantic correlation between user-defined words associated with neurodegeneration, dementia and aging and proteins from the FLNC-, GRN- or VCP-specific datasets." (PMID 26555887, 2015).
dementia (continued). "Furthermore, additional proteins which were consistently altered in both the FLNC-, GRN- and VCP-unique datasets, e.g. GFAP, NPTN, DBI, PRDX6, MARCKS and BSN, are closely associated with cognitive function, dementia and pathological aging." (PMID 26555887, 2015).
breast carcinoma (25 papers, 2008 to 2025). "Valosin-containing protein (VCP) is known to be a prognostic biomarker in breast carcinoma, and mutations in VCP are known to show clinical phenotype for FTD." (PMID 37834358, 2023). "Either loss of FAF1 or disassembly of the FAF1/VCP/βTRCP complex via AKT phosphorylation can lead to increased breast cancer metastatic potential." (PMID 28443643, 2017). "Further research is needed to elucidate the molecular mechanism underlying VCP-mediated BBB disruption fully and to evaluate the efficacy of VCP-targeted therapies in preclinical models of breast cancer brain metastasis." (PMID 39802400, 2025). "Cells overexpressing VCP exhibited significantly higher permeability to breast cancer cells passing through the pores compared to the control cells." (PMID 39802400, 2025). "This study provides compelling evidence for a novel role of VCP in promoting breast cancer brain metastasis through its impact on BBB integrity and function." (PMID 39802400, 2025). "Higher expression of VCP than MVP was verified in all healthy tissues representing secondary sites for breast cancer metastasis (breast, brain, bone, liver, lung, and lymph node)." (PMID 39802400, 2025). "Our findings identify VCP as a key player in disrupting the endothelial monolayer phenotype, with significantly higher levels observed in sEV derived from brain-tropic breast cancer cells compared to their parental counterparts." (PMID 39802400, 2025). "Mechanistically, VCP inhibition in breast cancer cells intensifies proteotoxic stress by restoring translation, thereby contributing to the occurrence of paraptosis." (PMID 38218922, 2024). "Similar to our findings, accumulation of ubiquitinated proteins has been observed in breast cancer upon VCP inhibition and in multiple myeloma cell lines upon genetic suppression or inhibition of VCP." (PMID 36923647, 2023). "For example, genes such as VCP, which has a role in breast cancer, and WFS1, which has a role in COVID-19, are known to show a role in FTD as well." (PMID 37834358, 2023). "When the expression of key gp78-mediated ERAD pathway was evaluated in a breast cancer cell panel, we found that p97/VCP, Derlin1, and gp78 expression was higher only in MCF-7 and BT474 cells." (PMID 37408196, 2023). "VCP promotes cancer cell proliferation or invasion and metastasis in lymphoma, colorectal cancer, prostate cancer, lung cancer, breast cancer and pancreatic cancer." (PMID 37606987, 2023). "KLF8 induces breast cancer (BC) invasion through the epithelial-stromal interaction 1/valosin-containing protein/NF-κB signaling pathway, which results in the degradation of IκBα and subsequent activation of NF-κB in the nucleus." (PMID 36761967, 2023). "Data analysis using TCGA database showed that VCP is elevated in several tumor types, such as breast cancer, colorectal cancer, and HCC." (PMID 35562734, 2022). "Compared to normal mammary epithelial cells, the expression of VCP was significantly higher in the cytoplasm of breast cancer cells." (PMID 35841038, 2022). "VCP/p97 also plays an important and crucial role in breast cancer, the most common cancer in women overall." (PMID 34576340, 2021). "Using an orthotopic tumor model, breast cancer cells and mammospheres, the effects of VCP/p97 on cancer and CSC proliferation were examined." (PMID 34576340, 2021). "First, immunohistochemical staining of human breast cancer tissues showed higher expression of VCP/p97 than in normal tissues and its correlation with the histological grade, tumor size, and lymph node metastasis." (PMID 34576340, 2021). "The serine/threonine kinase Akt is an important mediator of cell survival and cell proliferation and VCP has been shown to be a target of Akt signaling in neuronal cells and breast cancer cells." (PMID 23383273, 2013).
breast carcinoma (continued). "Surprisingly, elevated serum VCP levels were detected in clinically significant proportions of patients with ovarian carcinoma (8 of 8), breast cancer (5 of 12), colon cancer (7 of 12), pancreatic cancer (8 of 12) or non-Hodgkin's lymphoma (5 of 12)." (PMID 22870330, 2012). "VCP contributes to ATP-dependent cellular processes and is required for the survival of breast cancer cells." (PMID 18545673, 2008). "Our findings suggest that VCP represents a potential therapeutic target in breast cancer." (PMID 39802400, 2025). "Furthermore, significantly enhanced overall survival rates was observed in cases of gingival squamous cell carcinoma and breast carcinoma in patients with low VCP/p97 expression." (PMID 41357812, 2025). "We further examined the impact of VCP inhibition on other breast cancer cell lines." (PMID 38218922, 2024). "Interestingly, patients with high levels of VCP expression had poorer overall survival; therefore, VCP expression is suggested as an independent prognostic factor in breast carcinoma." (PMID 35841038, 2022). "In 2015, VCP/p97 overexpression was detected in breast cancer tissues compared to normal tissues using immunohistochemistry and correlated with decreased overall survival rates of these patients, which highlighted VCP/p97 as a useful prognostic biomarker in breast carcinoma." (PMID 34576340, 2021). "Taken together, these results suggest that VCP overexpression may compromise the integrity of the endothelial barrier, modulating gene expression and cellular function, leading to increased permeability and transmigration of breast cancer cells." (PMID 39802400, 2025). "Taken together, our results suggest a mechanistic model where tumor-derived sEV enriched with VCP contributes to BBB disruption and breast cancer brain metastasis." (PMID 39802400, 2025). "The results indicated that RUVBL1-AS1 might regulate cell cycle by modulating VCP expression, thereby decreasing the sensitivity to paclitaxel in HER2+ breast cancer." (PMID 40143733, 2025). "This study reveals that targeting VCP selectively eliminates breast cancer cells while sparing non-transformed cells by inducing paraptosis, a non-apoptotic cell death mechanism characterized by endoplasmic reticulum and mitochondria dilation." (PMID 38218922, 2024). "The expressions of p97/VCP and SVIP mRNA in tumor tissue were clearly higher than in normal tissue for most cancers, including prostate, pancreatic, acute myeloid leukemia, colon, rectal, and breast cancers." (PMID 39473740, 2024). "In this study, we present evidence that VCP inhibition preferentially induces cytotoxicity in breast cancer cells when compared to non-transformed cells, primarily through the induction of paraptosis." (PMID 38218922, 2024). "Since we showed that VCP activity controls basal MTDH expression levels, the careful use of pharmacological VCP activators might attenuate the progression of breast cancer." (PMID 38727283, 2024). "VCP/p97 was expressed at higher levels in this cellular subset than in the respective non-CSC populations in human breast cancer tissues and cells, and VCP/p97 expression positively correlated with SOX2, a CSC marker." (PMID 34576340, 2021). "Notably, VCP-mediated protein regulation and ERAD play vital roles in breast cancer CSCs." (PMID 39820491, 2025). "Importantly, our findings demonstrate that inhibiting VCP leads to preferential cell death in breast cancer cells compared to non-transformed cells, primarily through the induction of paraptosis." (PMID 38218922, 2024). "Other preclinical studies have also shown that genetic suppression or pharmacologic inhibition of VCP limits cell viability and/or induces apoptosis in breast cancer, human choriocarcinoma, multiple myeloma, non-small cell lung cancer (NSCLC), esophageal carcinoma, and ovarian cancer." (PMID 36923647, 2023).
breast carcinoma (continued). "In support, CBT worked additively with SAHA to induce radioiodide uptake in parental breast cancer MDA-MB-231 and MCF7 cells without affecting NIS mRNA or VCP protein." (PMID 34520744, 2022). "Moreover, serum VCP levels were increased in some GCT, ovarian carcinoma, breast cancer, and colon cancer patients who did not otherwise display increased levels of widely used serum tumor markers for their cancer type (e.g. inhibin A, inhibin B, CA125, CEA, or CA15.3)." (PMID 22870330, 2012).
proteinopathies (25 papers, 2012 to 2025). "Consistent with this possibility, we observed that G3Ia and G3Ib can induce the disassembly of aberrant stress granules triggered by the expression of a pathogenic VCP A232E mutation that causes multisystem proteinopathy." (PMID 38284934, 2024). "VCP resides in both the cytosol and the nucleus and different dominant mutations in VCP causing multisystem proteinopathy were reported to suppress the nuclear entry of VCP." (PMID 38701207, 2024). "One proteinopathy called multisystem proteinopathy (MSP) is associated with dominant mutations in Valosin Containing Protein (VCP)." (PMID 35414105, 2022). "Research focus on mutations in protein homeostasis genes such as VCP are helping to develop a more accurate picture of ALS proteinopathies through the emergence of the concept of the neurodegenerative disease termed multi system proteinopathy (MSP)." (PMID 35002606, 2021). "The key role of p97/VCP in protein homeostasis is indicated by its association with various diseases including cancer and with protein aggregates characteristic of proteinopathies linked to many neurodegenerative diseases." (PMID 23226521, 2012). "In addition, we showed that VCP proteinopathy mutations cause the accumulation of DNA damage in human neurons which can be prevented by modulating the levels of p37." (PMID 38701207, 2024). "Future studies aimed at defining the molecular components and mechanism related to VCP associated aggregate seeding may lead to therapies targeting multiple proteinopathies and degenerative diseases." (PMID 35414105, 2022). "Secondly, in a study of the effect a pathogenic mutation in a gene encoding an RNA binding protein, hnRNP A2/B2, that, in common with mutations in the FALS gene VCP causes multisystem proteinopathy, it was found to have a profound effect on the splicing of DAO." (PMID 29194436, 2017). "Mutations in gene encoding sequestosome 1/p62 (SQSTM1) and valosin containing protein (VCP) also contribute to proteinopathies and immune dysregulation by impairing autophagy and the degradation of aggregated protein." (PMID 37307819, 2024). "The ability of VCP mutations to affect multiple tissue types and diverse disease phenotypes reflects the complexity of ALS proteinopathies, with the VCP phenotype likely modulated by genetic and environmental factors." (PMID 35002606, 2021). "The proper knowledge on VCP activity in this pathway could help in understanding the pathological mechanisms of VCP-related diseases, possibly opening new therapeutic approaches in proteinopathies." (PMID 35216053, 2022). "Indeed, several other genes are associated with TDP-43 proteinopathies as well, with the most important ones being C9ORF72 in the ALS-FTD spectrum and VCP (valosin containing protein), hnRNPA1 and hnRNPA2B in multisystem proteinopathies (MSP)." (PMID 35185458, 2022). "An increasing body of evidence indicates that TDP-43 proteinopathy underlies motor neuron degeneration caused by diverse genetic defects in various hereditary ALS, including ubiquilin 2, profilin-1, optineurin, valosin-containing protein (VCP), and C9ORF72." (PMID 23300771, 2012). "It has been hypothesized that key proteins associated with ALS proteinopathies including TDP-43, FUS, VCP, and hnRNPA1 are examples of ‘essential’ proteins capable of starting a snowballing pathophysiological cascade due to their widespread roles or large numbers of downstream binding partners." (PMID 35002606, 2021).